TF (transferrin)
Diseases named in the same sentence as TF in open-access papers (continued):
Sharing a sentence is not in itself a finding about the gene and the disease.
liver cancer (22 papers, 2017 to 2025). An epithelial or non-epithelial malignant neoplasm that arises from the liver. "Transferrin saturation of 60% or higher is associated with a significant increase in the likelihood of liver cancer." (PMID 39170693, 2024). "The associations between liver cancer with iron and transferrin saturation remained consistent after adjustment for genetically predicted tobacco and alcohol consumption, while the other genetic associations were weakened or insignificant." (PMID 39170693, 2024). "Among the three protein isoforms encoded by the TF gene, SEPepQuant connected this specific isoform to liver cancer development and prognosis." (PMID 37726316, 2023). "Transferrin saturation showed increased risk of liver cancer, but transferrin levels presented a decreased risk." (PMID 35105367, 2022). "From the ENCODE TF ChIP-seq data, 5 transcription factors in liver cancer cell HEPG2 were enriched to regulate the poorly differentiated DEGs." (PMID 28415592, 2017). "Moreover, high transferrin saturation (≥60% versus <50%) was reported to be associated with a significant 5.9-fold higher risk of liver cancer in a prospective cohort of 8763 Danish adults followed up for 15 years." (PMID 32092884, 2020). "The Transferrin-modified NPs loaded with acetylcholinesterase gene (Tf-PL/AChE) significantly inhibited the proliferation of liver cancer in vivo." (PMID 40321406, 2025). "Higher levels of transferrin saturation were linked to a decreased risk of celiac disease, but a higher risk of non-alcoholic fatty liver disease (NAFLD) and liver cancer." (PMID 39170693, 2024). "Genetically predicted higher levels of transferrin saturation were linked to a lower risk of esophageal cancer and celiac disease, but a higher risk of CD, NAFLD, and liver cancer." (PMID 39170693, 2024). "Higher levels of transferrin saturation were proven to increase the risk of NAFLD, alcoholic liver disease, and liver cancer, but decrease the risk of esophageal cancer." (PMID 39170693, 2024). "Currently, the most often employed ligands in liver cancer therapy include galactose, glycyrrhetinic acid, folate, and short peptides, as well as macromolecular ligands such as transferrin (Tf), aptamers, antibodies." (PMID 35532174, 2022). "Several cfRNAs specific to liver cancer are genes known to be specifically expressed in the liver (TF, HRG, CP, and FGA)." (PMID 35816095, 2022). "In this work, we put forward a strategy for the delivery of the AChE gene by the transferrin modified liposome targeting TfR on the surface of liver cancer cells for liver cancer therapy." (PMID 33482834, 2021). "DOX@Fe-HMON-Tf NPs had surface-modified transferrin, and transferrin receptor-overexpressing liver cancer cells had a high affinity for them." (PMID 34749740, 2021). "This study proposed a transferrin-modified proteolipid-mediated gene delivery strategy for targeted liver cancer treatment, which has a promising potential for precise personalized cancer therapy." (PMID 33482834, 2021). "In conclusion, the strategy of combining the transferrin liposome and AChE gene provides a new idea for gene therapy of liver cancer." (PMID 33482834, 2021). "Herein, we prepared transferrin-modified liposomes (Tf-PL) for the targeted delivery of acetylcholinesterase (AChE) therapeutic gene to liver cancer." (PMID 33482834, 2021). "Genetically predicted higher levels of transferrin saturation were linked to a decreased risk of celiac disease (OR: 0.99, 95% CI: 0.99—0.99), but a higher risk of NAFLD (OR: 1.18, 95%CI: 1.08—1.28) and liver cancer (OR: 1.40, 95%CI: 1.17—1.67)." (PMID 39170693, 2024). "Higher levels of transferrin saturation were proven to increase the risk of NAFLD (OR: 1.18, 95%CI: 1.08—1.29), alcoholic liver disease (OR: 1.18, 95%CI: 1.00—1.39), and liver cancer (OR: 1.42, 95%CI: 1.17—1.72), but decrease the risk of esophageal cancer (OR: 0.83, 95%CI: 0.71—0.97)." (PMID 39170693, 2024).
liver cancer (continued). "However, its anti-cancer activity can be enhanced by forming drug-protein adducts with transferrin (TF) as was demonstrated in lung and liver cancer cells." (PMID 35047402, 2021). "Therefore, the use of transferrin for targeting TP-containing liposomes may prove to be an effective nanomedicine for the treatment of liver cancers." (PMID 37893242, 2023). "The OR of liver cancer was 2.45 (95% CI, 0.81, 7.45; p = 0.11), 2.11 (95% CI, 1.16, 3.83; p = 0.02), 10.89 (95% CI, 2.44, 48.59; p = 0.002) and 0.30 (95% CI, 0.17, 0.53; p = 2 × 10−5) for one SD increase in genetically predicted serum iron, log10 ferritin, ferritin saturation and transferrin levels." (PMID 32092884, 2020). "The odds ratios of liver cancer were 2.45 (95% CI, 0.81, 7.45; p = 0.11), 2.11 (1.16, 3.83; p = 0.02), 10.89 (2.44, 48.59; p = 0.002) and 0.30 (0.17, 0.53; p = 2 × 10−5) for one standard deviation increment of serum iron, transferrin saturation, ferritin and transferrin levels, respectively." (PMID 32092884, 2020). "In addition, reaching a transferrin saturation level of 60% or higher, as opposed to less than 50%, was found to be linked with a substantial 5.9-fold rise in the likelihood of developing liver cancer." (PMID 39170693, 2024).
depression (21 papers, 2016 to 2025). "Third, we did not assess participants’ iron metabolism parameters (e.g., serum ferritin, transferrin saturation) or depressive symptoms, which prevented further analysis of the associations between SN echogenicity, iron status, and depression." (PMID 41515535, 2025). "Our study findings indicate that young adult females with ferritin deficiency have lower odds of depression while young adult males with ferritin, serum iron, and transferrin deficiencies have higher odds of depression." (PMID 38226328, 2024). "Genetically predicted serum iron, ferritin, and transferrin saturation were positively associated with depression and psychogenic disorder, and inversely associated with gender identity disorders." (PMID 36590208, 2022). "The combined associations of genetic liability to depression and smoking initiation and genetically predicted higher levels of serum ferritin and transferrin saturation with epilepsy persisted at p ≤ .004 in meta‐analyses of data from the two sources." (PMID 33655641, 2021). "In detail, genetic liability to depression and smoking initiation and genetically predicted serum ferritin and transferrin saturation showed robust positive associations with epilepsy risk." (PMID 33655641, 2021). "Specifically, genetically predisposition to depression and smoking initiation, and high levels of serum iron, ferritin, and transferrin saturation were associated with increased risk of epilepsy." (PMID 33655641, 2021). "In this regard, lower transferrin and ferritin levels have been associated with depressive symptomatology in older individuals, and increased iron deposition in the thalamus and putamen has been shown in patients with depression." (PMID 39980634, 2025). "TF and TfR1 mediated iron metabolism and transport deficiency may contribute to the pathophysiological process of depression, and therefore may be a potential novel therapeutic target for stress-induced mental disorders." (PMID 36291201, 2022). "The most relevant predictive variables were potassium (K), folic acid, alkaline phosphatase, height, transferrin, body weight, BMI, triglyceride (Tg), Beck depression inventory score, and insulin." (PMID 40284254, 2025). "The main predictive variables identified were potassium (K), folic acid, alkaline phosphatase (ALP), height, transferrin, weight, body mass index (BMI), triglyceride (Tg), Beck Depression Test score, and insulin levels." (PMID 40284254, 2025). "Secondary outcomes included serum ferritin, transferrin saturation, the Edinburgh Postnatal Depression Scale (EPDS) score, and adverse events at 4 weeks." (PMID 40073039, 2025). "The pooled ORs for per SD unit increase of transferrin on psychogenic disorder, depression, and gender identity disorders were 1.30 (95%CI: 1.13, 1.48); P < 0.001, 1.29 (95%CI: 1.03, 1.62; P = 0.03), and 0.73 (95%CI: 0.68, 0.78; P < 0.001), respectively." (PMID 36590208, 2022). "TF is synthesized primarily in the liver and can cross the blood-brain barrier (BBB), and depression and vulnerability to chronic social stress are associated with loss of this barrier integrity." (PMID 36291201, 2022). "Together, this study provides a novel insight into the potential roles of TF in the liver and its receptor TfR1 in the brain in stress-induced depression." (PMID 36291201, 2022). "Interestingly, we also noticed that the upregulated level of serum TF in the susceptible mice was even higher than that of the resilient mice, suggesting the potential correlation between the serum concentration of the TF and the associated stress-induced depression." (PMID 36291201, 2022). "PD-RLS group had longer duration, higher stage and scores of motor symptoms, depression, anxiety, sleep disorders, fatigue and apathy, and increased transferrin and decreased iron, ferritin, dopamine (DA) and 5-hydroxytryptamine (5-HT) in CSF." (PMID 28874701, 2017).
depression (continued). "Furthermore, bioinformatics analysis of the Gene Expression Omnibus (GEO) database from various mouse models of depression revealed the significantly upregulated transcripts of TF and its receptor TfR1 in multiple brain regions in depressed mice." (PMID 36291201, 2022). "Moreover, the upregulated expression of TF and TfR1 in peripheral organs, such as blood and spleen, and central brain can be found in various depression mouse models including CSDS, PTSD, handling and restraint-induced depression." (PMID 36291201, 2022). "There is, however, evidence in the literature that depression is accompanied by alterations in iron metabolism, including decreased levels of iron and transferrin, as well as elevated levels of serum ferritin, reduced number of erythrocytes, and lower haematocrit and haemoglobin." (PMID 32962047, 2020). "In fatigue group, mental fatigue score is negatively correlated with 5-HT level in CSF, and positively correlated with the scores of depression and excessive daytime sleepiness, and disease duration, also, mental fatigue is positively correlated with the levels of iron and transferrin in CSF." (PMID 28442790, 2016). "Therefore, we next mainly focus on the potential role of TF in CSDS-induced mice with depression." (PMID 36291201, 2022). "Given that TF is synthesized primarily in the liver and can cross the blood-brain barrier, our study provides a possible working model that TF and its receptor TfR1 might mediate the pathophysiological responses in stress-induced mental disorders, such as anxiety and depression." (PMID 36291201, 2022). "The results indicated higher expression levels of TF and TfR1 in the peripheral blood and brain of CSDS-induced depression mouse models compared to the control group." (PMID 38259274, 2023). "Thus, our study provides a possible working model that peripheral TF transportation and its receptor TfR1 in the central nervous system might mediate the pathophysiological responses in stress-induced mental disorders, such as anxiety and depression." (PMID 36291201, 2022). "Meanwhile, to further explore the correlation between the expression level of TF and the sensitivity of CSDS-induced depression, we compared the concentration of TF in the liver and blood serum among the non-stressed control, the resilient mice, and the susceptible mice by ELISA analysis." (PMID 36291201, 2022).
Parkinson disease (21 papers, 2013 to 2026). A progressive degenerative disorder of the central nervous system characterized by loss of dopamine producing neurons in the substantia nigra and the presence of Lewy bodies in the substantia nigra and locus coeruleus. "Ligands such as nerve growth factors (NGFs), dopamine, transferrin (TF), and lactoferrin have additionally been investigated to target certain neuronal populations that partake in diseases like Alzheimer's and Parkinson's." (PMID 41356731, 2025). "Specifically, transferrin acts as an iron transporter and has been reported to decrease iron accumulation in Parkinson’s disease-affected neurons." (PMID 40136710, 2025). "Only scattered reports of iron status in people with parkinsonism were otherwise published before 1980; for instance, slightly elevated CSF level in one of two patients with parkinsonism, but normal serum and urinary levels of iron, transferrin, and ferritin." (PMID 35534717, 2022). "We evaluate the differences in serum transferrin sialylation in prodromal and early‐stage Parkinson's disease (PD), its relation to substantia nigra degeneration, and the risk of phenoconversion to manifest disease." (PMID 35128728, 2022). "Similar transferrin-based brain targeting was used to deliver puerarin to treat Parkinson’s disease (PD)." (PMID 35740342, 2022). "The transferrin/transferrin receptor 2 (Tf/TfR2) transport system has been reported to deliver transferrin-bound iron to mitochondria, which is disrupted in Parkinson’s disease." (PMID 34299144, 2021). "Comparison of iron, ferritin, and transferrin peripheral blood levels between patients with Parkinson’s disease and controls." (PMID 26751079, 2016). "For example, it has been reported that plasma transferrin level correlates with the tremor-dominant phenotype of Parkinson’s disease, as well as the abnormally low iron in PD patients was especially pronounced for subjects of haptoglobin Hp 2-1 phenotype, which also have higher risk of PD." (PMID 31616238, 2019). "The results also showed a number of genes that decreased in an Mn dose-dependent manner which include genes involved in iron transport (TF), protective activity of telomeres (TERF2), neurosensory function (MYO15a, OR1F1), and neurological disease such as ADHD (DIRAS2) and Parkinson’s disease (FRK)." (PMID 31396262, 2019).
viral infection (20 papers, 2012 to 2025). "To disrupt the capsid-vRNA interaction, we used the 9900 mutant sequence, which was engineered with silent mutations in the 6K/TF region to weaken this interaction, as previously shown by quantitative immunoprecipitation (qIP) following viral infection." (PMID 41081507, 2025). "It is believed that the CP and TF expression levels in the epithelial cells of genetically susceptible hosts may be significantly reduced when exposed to the joint action of virus infection and hormone factors." (PMID 37656227, 2023). "Using CpG as an optimal TLR9 agonist and focusing on early events after virus infection, we found that after pDC activation more of the pDC chromatin landscape is "turned on" rather than "turned off“, both globally in the genome and also among the regions associated with TF genes themselves." (PMID 34544361, 2021). "In existing studies of viral infections and iron in children, decreased levels of serum hemoglobin, iron and plasma transferrin saturation were observed during infection." (PMID 38907196, 2024). "While the axes IL-1β/IL-6 link to CRP production in bacterial infections, IL-18 production links to transferrin in viral infection." (PMID 35663992, 2022). "Further analysis is needed to determine the physiological implications of coordinated TF expression patterns, and their role in virus infection." (PMID 33799566, 2021). "To assess the impact of pDC activation on global TF expression in these cells, we simulated early events after virus infection in a time course study." (PMID 34544361, 2021). "One NAC TF gene, LrNAC35, was identified to be consistently and significantly up‐regulated upon virus infection." (PMID 31560826, 2019). "Using a text-mining approach we have uncovered some Pi-responsive TF genes to be involved in viral infection, cold acclimation and even pollen tube growth (PTG)." (PMID 22553952, 2012). "DMF and 4-OI protected against aberrant TF-mediated thrombin generation in vivo in models of bacterial- (both gram-negative and gram-positive) and viral infection and via multiple routes of administration." (PMID 37316487, 2023). "We observed different phenotype change in fungal colony color which turns yellow after virus infection without greater reduction of mycelial growth in some TF deletion mutants." (PMID 33643250, 2021). "Interestingly, DoRothEA analysis predicted that the TF Zeb2, known to promote the function of long-lived effector cells (LLECs) and effector memory CD8 T cells in acute viral infection, is active in splenic effector memory, AY036118+, and Cx3cr1+ effector cells." (PMID 35667687, 2022). "As apoptotic cells are one of the sources of circulating MPs, the impact of functional TF expression on the complex immunopathogenesis of liver fibrosis is likely a balance between endothelial cell apoptosis and inflammatory monocyte/macrophage origins of MPTF in viral infection." (PMID 25884329, 2015). "In addition, cell biological controls such as transferrin uptake for CME were more sensitive to pertubation than virus infection (data not shown)." (PMID 22536154, 2012).
gastric cancer (18 papers, 2006 to 2025). A primary or metastatic malignant neoplasm involving the stomach. "The glycan array established that hRTL preferentially recognized type-3 (Galβ1-3GalNAc) and type-1 galactosides, such as the TF-antigen and lacto N-biose, inducing cytotoxicity in gastric cancer cells, such as DLD-1, which expresses the mucin-associated TF-antigen." (PMID 39330281, 2024). "The combined use of arginine and glutamine in enteral and parenteral nutrition for patients after gastric cancer surgery has led to increased levels of albumin, serum protein, and transferrin, as well as decreased levels of C-reactive protein, C3, and C4." (PMID 39897929, 2025). "For example, truncated O-glycans including GalNAcα- (Tn), Neu5Acα2,6-Tn (sTn) Galβ1,3-GalNAcα- (TF), Neu5Acα2,6-TF, and Neu5Acα2,3-TF are found in breast, prostate, colon, respiratory, pancreas, ovarian, and gastric cancers." (PMID 39337716, 2024). "The Thomsen–Friedenreich (TF) antigen was previously found to be a potential single marker to identify MSI-high gastric cancers." (PMID 33572915, 2021). "This is related to the similarities between blood group A carbohydrate antigens and gastric cancer A-like Thompsen–Friedenreich (TF) antigen, with a resulting lowered host TF agglutinin response." (PMID 32899442, 2020). "MTT results showed that Cerium alone and in the presence of transferrin carries an increased significant mortality rate in adenocarcinoma cancer cells isolated from patients with gastric cancer (p=0.047)." (PMID 26664465, 2015). "As a vital TF exhibiting higher transcriptional activity in PTC samples than in control, EGR2 functions as a tumor suppressor that is generally decreased in numerous cancer types such as ovarian and gastric cancer." (PMID 29351231, 2018). "In several tumour entities, like colon, lung or gastric cancer, or in cancer of the cervix uteri, a correlation between TF expression and negative prognosis could be identified." (PMID 27825375, 2016). "It was also shown that the examined TF bound to construct with rs10815225 G allele but not to construct with C allele and that the up-regulation or silencing of SP1 resulted respectively in elevated or decreased PD-L1 expression on mRNA and protein level in SGC-7901 cells (gastric cancer cell line)." (PMID 33255938, 2020). "Our data indicate that the TF antigen is not a predictor of MSI in CRC, contrary to what has been described in gastric cancer with MSI." (PMID 33572915, 2021).